RNU6-697P (RNA, U6 small nuclear 697, pseudogene)
Gene: Small nuclear RNA gene on chromosome 10 (68,846,805 to 68,846,911, forward strand). Ensembl gene ENSG00000200218.
Homologues: Orthologues: macaque U6 (93% identical). Paralogues in human: RNU6-797P (87% identical), RNU6-1309P (86% identical), RNU6-727P (86% identical), RNU6-1091P (85% identical), RNU6-1209P (85% identical), RNU6-175P (85% identical), RNU6-1022P (84% identical), RNU6-1083P (84% identical), RNU6-11P (84% identical), RNU6-16P (84% identical), RNU6-28P (84% identical), RNU6-37P (84% identical), and 1285 more.